FKBP10 (FKBP prolyl isomerase 10)
Diseases named in the same sentence as FKBP10 in open-access papers (continued):
Sharing a sentence is not in itself a finding about the gene and the disease.
idiopathic pulmonary fibrosis (9 papers, 2017 to 2025). Idiopathic pulmonary fibrosis (IPF) is a nonneoplastic pulmonary disease that is characterized by the formation of scar tissue within the lungs in the absence of any known cause. "Similarly, a few studies showed that FKBP10 is implicated in inducing lung fibrosis through the activation of the TGF-beta pathway, whereas FKBP13 showed a conflicting role in lung fibrosis." (PMID 36302992, 2023). "FKBP10 was reported to be upregulated in experimental lung fibrosis and idiopathic pulmonary fibrosis (IPF), where it is mainly expressed by (myo)fibroblasts." (PMID 39272983, 2024). "FKBP10 overexpression was found in lung fibroblast of idiopathic pulmonary fibrosis (IPF), leading to an impact on extracellular matrix protein synthesis and secretion." (PMID 33557829, 2021). "Thus, FKBP10 is an important therapeutic target for the treatment of pulmonary fibrosis in myofibroblasts." (PMID 41477319, 2025). "Interestingly, FKBP10 knockdown in idiopathic pulmonary fibrosis significantly reduced the expression of collagen I, V, and fibronectin." (PMID 36302992, 2023). "Nintedanib approved for idiopathic pulmonary fibrosis therapy significantly could down-regulate FKBP10 expression in IPF fibroblasts." (PMID 33557829, 2021). "A previous study demonstrated that FDA-approved nintedanib for Idiopathic Pulmonary Fibrosis (IPF) therapy could downregulate FKBP10 expression in IPF fibroblasts." (PMID 37201304, 2023). "Taken together, cyclophilin A, FKBP12, FKBP10, and, FKBP13 have shown an important role in the pathogenesis of lung fibrosis; however, further research should be conducted to strengthen their therapeutic target potential in lung fibrosis treatment." (PMID 36302992, 2023). "Recently another member of this family FKBP10 has been shown to play a role in collagen processing and might thus modulate ECM composition in interstitial fibroblasts in idiopathic pulmonary fibrosis (IPF)." (PMID 29255427, 2017).
colorectal cancer (6 papers, 2021 to 2026). A primary or metastatic malignant neoplasm that affects the colon or rectum. "Additionally, FKBP10, which drove colorectal cancer progression and was associated with a poor prognosis, might be an essential prognostic risk factor." (PMID 36463181, 2022). "Recent studies have shown the upregulation of FKBP10 in various cancers, including clear cell renal cell carcinoma, colorectal cancer, gastric cancer and lung adenocarcinoma 15-18." (PMID 39781460, 2025).
bladder cancer (4 papers, 2022 to 2025). "Five genes in our prognostic model, ANXA1, MAP1B and SPOCD1 have been reported in bladder cancer, however DOK7 and FKBP10 has not been studied in bladder cancer." (PMID 36709279, 2023).
breast carcinoma (3 papers, 2020 to 2026). "FKBP10 has been studied in some cancers and its role is currently controversial, while few studies have investigated FKBP10 in breast cancer." (PMID 35096583, 2021). "In addition, relationships between KRT19, FKBP10 and GSK3B expression and clinicopathological features from TCGA breast cancer cohort (n = 1083) were also explored." (PMID 35096583, 2021).
lung adenocarcinoma (3 papers, 2021 to 2023). A carcinoma that arises from the lung and is characterized by the presence of malignant glandular epithelial cells. "FKBP10 is a novel biomarker for lung adenocarcinoma brain metastases, which is closely associated with survival time and may serve as a potential therapeutic target." (PMID 37201304, 2023). "In addition, the present study also demonstrates that FKBP10 is a novel biomarker for lung adenocarcinoma brain metastases, which is closely associated with survival time and may serve as a potential therapeutic target." (PMID 37201304, 2023). "Of the 71 patients with lung adenocarcinoma brain metastases, 39 (54.9%) had low and 32 (45.1%) had high FKBP10 expression." (PMID 37201304, 2023). "The authors found that higher FKBP10 expression was observed in lung adenocarcinoma than in normal lung tissue (p = 0.008), which depended on tumor stage (p < 0.001)." (PMID 37201304, 2023). "A public database was used to detect FKBP10 expression and its clinical value in primary lung adenocarcinoma." (PMID 37201304, 2023). "Survival analysis in public databases also indicates that FKBP10 is inversely correlated with the overall survival and disease-free survival of patients with primary lung adenocarcinoma." (PMID 37201304, 2023). "For lung adenocarcinoma patients with brain metastases, high expression of FKBP10 predicts a worse survival time than for those with low or no expression." (PMID 37201304, 2023). "The authors first analyzed FKBP10 expression in human primary lung adenocarcinoma using the CANCERTOOL database." (PMID 37201304, 2023). "In this study, the authors found that FKBP10 expression has an independent prognostic impact on the survival of lung adenocarcinoma patients with brain metastases." (PMID 37201304, 2023). "The authors found that FKBP10 expression was inversely correlated with the overall survival (p = 0.001) and disease-free survival (p = 0.004) time in patients with lung adenocarcinoma in the CANCERTOOL database." (PMID 37201304, 2023). "The authors also detected FKBP10 expression in primary lung adenocarcinoma using a public database, found that FKBP10 is also selectively expressed in primary lung adenocarcinoma, and affects the overall survival and disease-free survival of patients." (PMID 37201304, 2023). "The results showed that primary lung adenocarcinoma tissue had higher FKBP10 expression than normal lung tissue (p = 0.008)." (PMID 37201304, 2023). "The authors found that the FKBP10 protein was selectively expressed in lung adenocarcinoma brain metastases." (PMID 37201304, 2023). "•FKBP10 is a valuable prognostic indicator for lung adenocarcinoma." (PMID 37201304, 2023). "•FKBP10 proteins are highly expressed in lung adenocarcinoma, including brain metastasis tissue." (PMID 37201304, 2023). "In the present study, the authors detected the role of FKBP10 in lung adenocarcinoma brain metastases, analyzed survival, and found that FKBP10 was highly expressed in lung adenocarcinoma brain metastases, which has an independent prognostic impact on these patients." (PMID 37201304, 2023). "•FKBP10 is a potential clinical biomarker for lung adenocarcinoma." (PMID 37201304, 2023). "Further studies are needed to investigate whether nintedanib could improve the prognosis of high FKBP10-expressing lung adenocarcinoma brain metastases." (PMID 37201304, 2023). "Moreover, the authors also investigated FKBP10 expression levels in primary lung adenocarcinoma using public databases." (PMID 37201304, 2023). "FKBP10-positive cells were detected in 39 patients (55%) with lung adenocarcinoma brain metastases." (PMID 37201304, 2023). "However, the clinical implications of FKBP10 in lung adenocarcinoma brain metastases remain unclear." (PMID 37201304, 2023). "However, the protein expression and clinical value of FKBP10 in brain metastases of lung adenocarcinoma remain unclear." (PMID 37201304, 2023).
lung adenocarcinoma (continued). "Thus, low FKBP10 expression may indicate less malignancy in lung adenocarcinoma brain metastases." (PMID 37201304, 2023). "The authors further analyzed the relationship between FKBP10 expression and EGFR mutation status and found that the expression of FKBP10 is similar between lung adenocarcinoma brain metastases bearing EGFR mutations and EGFR non-mutants." (PMID 37201304, 2023). "In the present study, the authors found that FKBP10-positive cells were only detected in brain metastatic lesions of lung adenocarcinoma and not in non-tumor brain tissue." (PMID 37201304, 2023). "The difference in FKBP10 positive rate between lung adenocarcinoma brain metastases tissue and non-tumor brain tissue was significant (p < 0.001), which indicated that FKBP10 expression is tumor-specific in the cohort of patients." (PMID 37201304, 2023). "Considering the clinical significance of FKBP10 in brain metastases and the fact that no previous study has explored its expression in primary tumor lung adenocarcinoma, the authors have investigated the relevance of FKBP10 in lung adenocarcinoma." (PMID 37201304, 2023).
renal cell carcinoma (3 papers, 2020 to 2025). "In addition, it is suggested that FKBP10 could be a new promising therapeutic target for the treatment of renal cell carcinoma." (PMID 31945087, 2020).
stomach adenocarcinoma (3 papers, 2022 to 2023). "In addition, FKBP10 promoted tumor cell proliferation, invasion, and migration in stomach adenocarcinoma, and similar findings were observed in ccRCC in this study." (PMID 36463181, 2022).
blepharoptosis (2 papers, 2020 to 2021). "Statistical analysis was conducted for WNT1, SERPINF1 and FKBP10, with > 3 probands, and only ptosis was significantly different between groups." (PMID 33093841, 2020).
melanoma (2 papers, 2016 to 2023). A malignant, usually aggressive tumor composed of atypical, neoplastic melanocytes. "To do so, we established B16F10 melanoma cells deficient in either NACC1 or FKBP10 and then injected them into immune-competent or immune-incompetent mice." (PMID 37406115, 2023). "Additional co-expression studies with defined gene signatures using Oncomine suggest an association of BAMBI and FKBP10 with the angiogenic process in melanoma and with regeneration after HRAS induced cell transformation, respectively." (PMID 27689402, 2016). "We focused on FKBP10 because of its strong expression in melanoma (up 15.18-fold)." (PMID 27689402, 2016). "Unlike NACC1, FKBP10 expression was not affected by NR2F6 loss in human melanoma cells." (PMID 37406115, 2023). "Given the correlation in melanoma specimens, we set to correlate NR2F6, NACC1, and FKBP10 expression with patients’ overall survival and response to ICT in other cancer types." (PMID 37406115, 2023). "To further assess candidate NR2F6 effectors, we first validated NACC1, FKBP10, and CXCL10 expression levels in NR2F6 KD or KO mouse melanoma cells." (PMID 37406115, 2023). "Whereas the role of TNC (tenascin C) and FN1 (fibronectin 1) in melanoma development is well documented, implication of MARCKS, RCN3, BAMBI, PEA3/ETV4 and the FK506 family members FKBP7, FKBP10 and FKBP11 in melanoma progression is unclear." (PMID 27689402, 2016). "In agreement, NR2F6 expression did not correlate with FKBP10 expression in melanoma cells [quantitative reverse transcription polymerase chain reaction (qRT-PCR) and cancer cell line encyclopedia (CCLE)]." (PMID 37406115, 2023). "Inhibition of NR2F6 expression by either shRNA KD or CRISPR-mediated KO inhibited melanoma growth in immune-competent but not immune-incompetent mice, an outcome phenocopied by NACC1 and FKBP10 loss." (PMID 37406115, 2023). "Important corroboration of our findings, tumor-intrinsic NR2F6, came from independent scRNA-seq analysis of human melanoma specimens: NR2F6, NACC1, and FKBP10 expression in malignant melanoma cells was significantly higher in samples from patients that are nonresponsive to anti–PD-1–based ICT." (PMID 37406115, 2023). "Our data suggest that FKBP10 could be a potential target in melanoma treatment, since HRAS specifically induces FKBP10 expression." (PMID 27689402, 2016). "Notably, patients whose melanoma specimens showed high NACC1 and FKBP10 expression exhibited the worst overall survival, and those specimens also exhibited the highest NR2F6 expression relative to specimens expressing low NACC1 and FKBP10." (PMID 37406115, 2023). "Notably, analysis of melanoma patient data provided important support for our findings, revealing higher expression of NR2F6/NACC1/FKBP10 in nonresponders to ICT." (PMID 37406115, 2023).
renal carcinoma (2 papers, 2025 to 2026). A carcinoma arising from the epithelium of the renal parenchyma or the renal pelvis. "Analyzes the ways in which FKBP10 impacts the response to HIF2α inhibitors and the development of renal cancer by increasing histone lactylation and enhancing LDHA phosphorylation." (PMID 39968078, 2025). "Identifies possible targets for treatment in the interactions between FKBP10 and LDHA to prevent metabolic reprogramming in renal cancer and increase the effectiveness of HIF2α inhibitors." (PMID 39968078, 2025). "Used in vivo studies, bioinformatics, and molecular biology methods to investigate the relationship between FKBP10 and LDHA and how it affects the course of renal cancer as well as treatment sensitivity." (PMID 39968078, 2025).
sarcoidosis (2 papers, 2021 to 2022). Sarcoidosis is a multisystemic disorder of unknown cause characterized by the formation of immune granulomas in involved organs. "The identification of germline mutations in the gene encoding FKBP10 (FK506-binding protein 10) is interesting due to the fact that it binds FK506 (tacrolimus), an immunosuppressive drug which has been used in cutaneous and cardiac refractory forms of sarcoidosis." (PMID 34440765, 2021). "SARS-CoV2 ORF8 host targets belonging to the sarcoidosis gene panel (IL17RA, EMC1, PLD3, GDF15, FKBP10, ADAM9, and PLAT) highlight significant pathways related to sarcoidosis pathogenesis." (PMID 34440765, 2021).
acute myeloid leukemia (1 paper, 2022). Acute myeloid leukemia (AML) is a group of neoplasms arising from precursor cells committed to the myeloid cell-line differentiation. "Notably, SERPINE1 and FKBP10 genes were found in the hematopoietic cell lineage (hsa04640), acute myeloid leukemia (hsa05221) and complement and coagulation cascades (hsa04610) pathways." (PMID 35571107, 2022).
adenoma (1 paper, 2023). A neoplasm arising from the epithelium. "We then compared the subcellular expression patterns of FKBP10 in normal, adenoma and CRC tissues and found that in almost all normal (98.4%) and adenoma (100%) tissues, FKBP10 was expressed as ‘FKBP10-C’, while only 15% of CRC tissues exhibited ‘FKBP10-C’ expression." (PMID 37511172, 2023).
autoimmune disease (1 paper, 2022). A disorder resulting from loss of function or tissue destruction of an organ or multiple organs, arising from humoral or cellular immune responses of the individual to their own tissue constituents. "While FKBP10, FKBP11 (this study), and FKBP2 have been reported in the context of IPF, others have demonstrated a role of FKBP11 in autoimmune disease." (PMID 35456020, 2022).
Autoimmunity (1 paper, 2026). The occurrence of an immune reaction against the organism's own cells or tissues. "Systemic inflammation and impaired collagen processing due to FKBP10 mutations might create an environment that facilitates autoimmunity." (PMID 41530856, 2026).
bladder tumor (1 paper, 2025). "In an orthotopic bladder tumor model, FKBP10 knockdown significantly inhibited muscle infiltration and lung metastasis." (PMID 39781460, 2025). "Next, we used the subcutaneous xenograft model, the orthotopic bladder tumor model and the lung metastasis model to investigate the effect of FKBP10 on BC progression in vivo." (PMID 39781460, 2025). "However, in the orthotopic bladder tumor model, FKBP10 knockdown significantly reduced the overall bladder weight." (PMID 39781460, 2025). "Next, we found that although FKBP10 did not promote cancer cell proliferation, FKBP10 promoted the migration and invasion of cancer cells, as well as the infiltration into the muscle layer in orthotopic bladder tumor model." (PMID 39781460, 2025).
breast tumors (1 paper, 2023). "scRNA-seq analysis of nonmetastatic primary breast tumors from patients subjected to a single dose of anti–PD-1 ICT revealed higher NR2F6 and FKBP10 expression in nonresponders [fig." (PMID 37406115, 2023).
colon adenocarcinoma (1 paper, 2023). "The results showed that the global transcriptional expression of FKBP10 was significantly elevated in colon adenocarcinoma (COAD) and rectum adenocarcinoma (READ) tissues compared with normal tissues, indicating a tumor promotive function of FKBP10." (PMID 37511172, 2023).
dentinogenesis imperfecta (1 paper, 2011). Dentinogenesis imperfecta (DGI) is a hereditary dentin defect characterized by abnormal dentin structure resulting in abnormal tooth development. "Taken together, our study shows that a severe, progressive course of OI type IV with pre- or perinatal onset of fractures and dentinogenesis imperfecta has to be added to the spectrum of clinical features that can be associated with FKBP10 mutations." (PMID 22107750, 2011). "Furthermore, it adds dentinogenesis imperfecta to the spectrum of clinical symptoms associated with FKBP10 mutations." (PMID 22107750, 2011). "Furthermore, dentinogenesis imperfecta was present in all three brothers but has so far not been described as a feature of patients with FKBP10 mutations." (PMID 22107750, 2011).
Dry skin (1 paper, 2023). Skin characterized by the lack of natural or normal moisture. "It is interesting, that most disorders have additional skin manifestations such as dry skin in both ARC syndrome and collagen VI disorders, and fragile skin in patients with PLOD2, FKBP10 and PLOD3 mutations." (PMID 37686358, 2023).
epidermolysis bullosa (1 paper, 2024). Epidermolysis bullosa (EB) is a group of genetic skin diseases that cause the skin to blister very easily. "Additionally, two unrelated patients with BS I and epidermolysis bullosa shared identical homozygous FKBP10 and KRT14 variants." (PMID 38927610, 2024).
Hepatic fibrosis (1 paper, 2024). The presence of excessive fibrous connective tissue in the liver. "We observed the upregulation of Fkbp10, a molecular chaperone found in the ER that fuels the progression of hepatic fibrosis." (PMID 38307876, 2024).
Obesity (1 paper, 2020). Accumulation of substantial excess body fat. "Only six out of the 81 mitochondrial protein-encoding genes showed higher expression in the obesity-risk genotype (SEPT4, PYCR1, PRELID2, CPT1A, MTHFD1L, and FKBP10)." (PMID 32316277, 2020).
pituitary adenomas (1 paper, 2023). "The expression levels of ANXA2, PMAIP1, SPRY2, C2CD4A, APOD, FGF14 and FKBP10 were significantly upregulated while FNDC5 and MAP3K4 were downregulated in the invasive gonadotrophic pituitary adenomas compared to the non-invasive ones." (PMID 36750863, 2023).
scoliosis (1 paper, 2023). A congenital or acquired spinal deformity characterized by lateral curvature of the spine. "In particular, all six patients with mutations in FKBP10 (type XI OI) had scoliosis." (PMID 37730650, 2023).
serous carcinomas (1 paper, 2021). "It is worthwhile to mention that FKBP10 has been reported to be underexpressed in high-grade serous carcinomas (HGSC) and absence of FKBP10 expression was strongly related to prolonged survival time of patients, which suggest FKBP10 may play a role of tumor suppressor in HGSC." (PMID 33557829, 2021).
skin cancer (1 paper, 2016). "FKBP7, FKBP11 and FKBP10, upregulated 3.21, 2.42 and 15.18-fold, respectively, have not yet been described in skin cancer." (PMID 27689402, 2016).
squamous cell carcinoma (1 paper, 2023). A carcinoma arising from squamous epithelial cells. "Some researchers performed FKBP10 immunohistochemistry analysis in 32 cases of healthy lung tissue and 160 cases of NSCLC (80 cases of each squamous cell carcinoma and adenocarcinoma) and they found that FKBP10-positive cells were detected only in cancer lesions and not in the healthy parenchyma." (PMID 37201304, 2023).